ASPN (asporin)
Diseases named in the same sentence as ASPN in open-access papers (continued):
Sharing a sentence is not in itself a finding about the gene and the disease.
colorectal cancer (8 papers, 2016 to 2023). A primary or metastatic malignant neoplasm that affects the colon or rectum. "Interestingly, cytoplasmic ASPN have been found to promote cell migration and indicate a poor prognosis in colorectal cancer, and elevated DKK1 expression is associated with recurrence and impairs the response to PD-1 blockade in dMMR CRC, while both of which are down regulated in IVE group." (PMID 34438367, 2021). "ASPN is also overexpressed in colorectal cancer tissues compared with adjacent normal tissues and its expression is associated with lymph node metastasis and TNM stage." (PMID 36358747, 2022). "Increased gene copy number variation is the main reason for the overexpression of ASPN in colorectal cancer tissues." (PMID 36011263, 2022). "In colorectal cancer, ASPN expression was significantly elevated and correlated with advanced clinicopathological features such as tumor size, disease recurrence, and poor prognosis." (PMID 36011263, 2022). "In colorectal cancer tissues, elevated co-expression of ASPN and p-cortactin (Tyr 241), an essential component for invadopodia formation and cellular migration, are found." (PMID 36358747, 2022). "When ASPN is overexpressed in HT-29 and LoVo colorectal cancer cells, the EGFR/Src axis is activated, leading to increased phosphorylation (Tyr 241) of cortactin." (PMID 36358747, 2022). "Here we found that besides being located in the stroma of CRC, most of the ASPN protein was located inside colorectal cancer cells, so that the possible intracellular function of ASPN should be given more attention." (PMID 30728352, 2019). "In vitro experiments show that ASPN enhances migration and invasion of colorectal cancer cells." (PMID 36358747, 2022). "miR-101 inhibits colorectal cancer progression through targeted modulation of ASPN." (PMID 36011263, 2022). "For example, miR-101 inhibits colorectal cancer through targeted regulation of ASPN." (PMID 34663368, 2021). "For colorectal cancer, a few preliminary studies suggested ASPN might be a potential biomarker for CRC detection." (PMID 30728352, 2019). "Asporin has been implicated as an oncogene in various types of human cancers; however, the roles of asporin in the development and progression of colorectal cancer (CRC) have not yet been determined." (PMID 27705916, 2016). "Here, we demonstrated a higher expression level of ASPN in colorectal cancer (CRC) than matched normal tissues, and 25% (2/8) CRC showed copy number variation (CNV) gain/amplification in ASPN gene." (PMID 30728352, 2019). "Cytoplasmic ASPN can recruit the TGFβ-induced p-SMAD2/3 on the nuclear membrane, facilitating their transportation to the nucleus inducing the expression of EMT-related genes, such as MMP-2, MMP-9, AHR, GLI2, ZEB1, TCF4, and TNC in colorectal cancer cells." (PMID 36358747, 2022). "As a potential oncogene, asporin might be a prognostic biomarker for CRC patients and it was a potential therapeutic target for colorectal cancer treatment." (PMID 27705916, 2016).
lumbar disc degeneration (7 papers, 2009 to 2024). "Asporin (Asp), which has been associated with lumbar disc disease in humans, was down-regulated in mutant IVD." (PMID 20214815, 2010). "Genetic studies of ASPN gene polymorphism have demonstrated an association between ASPN and various bone and joint diseases, including knee osteoarthritis, rheumatoid arthritis, and lumbar disc disease." (PMID 31665048, 2019). "Previous studies have shown that the ASPN D14 allele is a risk gene for knee osteoarthritis (OA) and the D13 allele is a protective genetic factor for OA, and recent studies have shown that the ASPN repeat polymorphism is associated with OA, lumbar disc degeneration (LDD), and DDH." (PMID 39156961, 2024). "To date, although the D14 allele of asporin has been reported to be associated with lumbar disc degeneration in Asian subjects, there have been no studies on the location of asporin in the intervertebral disc, or on the levels of gene expression in disc tissue, in Caucasian subjects." (PMID 19327154, 2009).
disc degeneration (6 papers, 2009 to 2022). "Secondly, we have not yet been able to examine our study population for the presence of the asporin polymorphisms now known to be present in Asian patients with disc degeneration." (PMID 19327154, 2009). "Although increased asporin has been reported during disc degeneration, the intricate underlying mechanism by which asporin becomes involved in the pathogenesis of disc degeneration remains largely unknown." (PMID 28646230, 2017). "It has recently been suggested that genetic polymorphisms associated with knee OA [e.g., in asporin and growth differentiation factor 5] may also be related to disc degeneration." (PMID 26552449, 2015). "Furthermore, expression of a particular asporin allele (D14) has been associated with the development of disc degeneration in both Chinese and Japanese populations." (PMID 24171898, 2013). "Here, we confirmed that asporin expression in nucleus pulposus tissues increased with disc degeneration." (PMID 28646230, 2017). "To explore the role of asporin in disc degeneration, we first evaluated the expression of asporin in the nucleus pulposus of patients with intervertebral disc degeneration." (PMID 28646230, 2017). "Our findings uncovered a vital detrimental role of asporin in promoting disc degeneration and delineated a previously unknown intrinsic regulatory mechanism." (PMID 28646230, 2017). "Therefore, animal models that are more clinically relevant are critical for assessing the function of asporin in disc degeneration." (PMID 28646230, 2017). "Further understanding of the role of this molecule in disc degeneration may provide greater insight into potential explanations for downregulation of asporin in organ culture models." (PMID 24171898, 2013). "Consistently, the increased asporin expression with degeneration was also proved by rabbit intervertebral disc degeneration (IDD) model." (PMID 28646230, 2017). "Therefore, the identification of asporin as a negative regulator of aggrecan and type Π collagen, as well as the elucidation of the mechanisms by which it is induced in human nucleus pulposus cells, may provide potential immune-based anti-disc degeneration therapies by targeting asporin expression." (PMID 28646230, 2017).
heart failure (6 papers, 2021 to 2023). Inability of the heart to pump blood at an adequate rate to meet tissue metabolic requirements. "We screened for differentially expressed genes in heart failure using available gene expression data from the Gene Expression Omnibus database and identified 6 important genes by a random forest classifier (ASPN, MXRA5, LUM, GLUL, CNN1, and SERPINA3)." (PMID 36254001, 2022). "Several ECM proteins detected in this study have already been proposed as potential markers of heart failure, including osteoglycan (mimecan), fibulin-3, biglycan, and asporin." (PMID 33670142, 2021). "It indicates that the role of ASPN in cardiomyocyte has been preliminarily confirmed, and ASPN may be a potential promising biomarker for heart failure." (PMID 35433865, 2022). "Our bioinformatics revealed downregulation of miR–129-5p and upregulation of its targets small leucine–rich proteoglycan Asporin (ASPN) and transcription factor SOX9 as common in mouse and human heart failure (HF)." (PMID 37154157, 2023). "In addition, in our analysis results, NPPA, NPPB, COL1A2, ASPN, ANKRD1 and CTGF were all confirmed to be closely related to heart failure in dilated cardiomyopathy in various studies." (PMID 34970603, 2021).
pulmonary fibrosis (6 papers, 2022 to 2025). Chronic progressive interstitial lung disorder characterized by the replacement of the lung tissue by connective tissue, leading to progressive dyspnea, respiratory failure, or right heart failure. "Downregulation of ASPN can inhibit abnormal myofibroblast development and protofibroblast gene expression in vitro, thereby blocking or reversing the progression of pulmonary fibrosis." (PMID 37869159, 2023). "Moreover, in our previous study, we demonstrated that ASPN could accelerate pulmonary fibrosis by promoting myofibroblast differentiation induced by TGF-β and play an important role during the pathological process of IPF." (PMID 37334348, 2023). "ASPN regulates the synthesis of extracellular matrix and collagen deposition through the TGF-β/Smad signaling pathway, thereby promoting progression of pulmonary fibrosis." (PMID 40273141, 2025). "ASPN, a member of the small leucine-rich repeat protein (SLRP) family, modulates ECM formation and fibroblast activation in various fibrotic conditions, such as idiopathic pulmonary fibrosis, cardiac fibrosis, and HTS." (PMID 40881699, 2025). "To further verify the differential expression of candidate hub genes between IPF and control samples, we then established a bleomycin-induced pulmonary fibrosis mouse model and detected the expression of SLCO4A1, ASPN and SFRP2 between fibrotic lung samples and control samples from model mice." (PMID 37334348, 2023).
joint diseases (5 papers, 2010 to 2022). "ASPN is a gene found in bone and joint diseases that encodes a small leucine-rich proteoglycan, an important component of extracellular matrix tissue proteins." (PMID 36011263, 2022). "Analysis of genetic polymorphism of the ASPN gene shows that ASPN is closely related to various bone and joint diseases." (PMID 34663368, 2021). "As an extracellular, tissue-specific protein, Asporin represents a promising target for pharmacogenomics approaches to common bone and joint diseases." (PMID 31665048, 2019).
Myocardial fibrosis (4 papers, 2022 to 2025). "Overexpression of miR-129-5p was able to downregulate ASPN expression, and targeting the miR-129-5p/ASPN signaling axis in cardiac fibroblasts attenuated myocardial fibrosis and calcification and restored cardiac function in mice." (PMID 41158506, 2025). "Myocardial fibrosis and cardiac remodeling are known as the pathological hallmarks of DCM, and the association of hub genes (MFAP4, ASPN, and FAP) with fibrosis and cardiac remodeling has been identified in prior research." (PMID 37869159, 2023). "Since both SOX9 and ASPN were validated to be upregulated in LV upon chronic AngII infusion, we pursued this in vivo model to further investigate the role of miR–129-5p in myocardial fibrosis and calcification in mice." (PMID 37154157, 2023). "We experimentally confirmed decreased miR–129-5p and enhanced SOX9 and ASPN expression in CF in human hearts with myocardial fibrosis and calcification." (PMID 37154157, 2023). "Together, we demonstrate miR–129-5p/ASPN and miR–129-5p/SOX9 as potentially novel dysregulated axes in CF-to-MF and CF-to-OF transition in myocardial fibrosis and calcification and the therapeutic relevance of miR–129-5p." (PMID 37154157, 2023). "Together, these data show dysregulated expression of miR–129-5p and its targets ASPN and SOX9 in mouse LV and human CF in the context of nonischemic HF associated with myocardial fibrosis and calcification." (PMID 37154157, 2023). "Importantly, miR–129-5p mimic not only attenuated progression of myocardial fibrosis, calcification marker expression, and SOX9 and ASPN expression in CF but also restored diastolic and systolic function." (PMID 37154157, 2023). "To assess whether the attenuation of myocardial fibrosis and calcification progression by miR–129-5p may be explained by differences in expression of SOX9 and ASPN in CF, we employed lineage tracing of CF of the transcription factor 21 (Tcf21) lineage in mice (Tcf21MCM/+;R26EGFP mice)." (PMID 37154157, 2023).
pancreatic cancer (4 papers, 2014 to 2022). "In pancreatic cancer, ASPN induces EMT in a paracrine manner via expression by pancreatic stellate cells." (PMID 36358747, 2022). "ASPN binds to CD44 in pancreatic cancer cells and activates the CD44/AKT/ERK-NF-kB signaling axis, which lead to EMT induction and increased migration and invasion." (PMID 36358747, 2022). "Little is known regarding the function of ASPN in pancreatic cancer, but it is supposed to have a role in TGF-beta/Smad signaling." (PMID 24708694, 2014).
Arthritis (3 papers, 2013 to 2019). Inflammation of a joint. "The two arthritis-susceptible candidate SNPs, rs7775 (p.Arg324Gly) in the FRZB gene and rs7033979 in the ASPN gene, showed associations with KBD (OR = 1.568, P = 4 × 10−3 and OR = 0.744, P = 8 × 10−3, respectively)." (PMID 28651521, 2017).
dilated cardiomyopathy (3 papers, 2021 to 2025). Cardiomyopathy which is characterized by dilation and contractile dysfunction of the left and right ventricles. "Regarding ASPN, the main associations were with Dilated Cardiomyopathy (DCM), ECM receptor interaction, Hypertrophic Cardiomyopathy (HCM), and the TGF-β signaling pathway." (PMID 40901835, 2025). "First, three Hub genes (MYH6, ASPN, and COL14A1) associated with dilated cardiomyopathy-related HF were identified using a large-scale training dataset." (PMID 41158506, 2025). "MYH6, ASPN, and COL14A1 may be potential biomarkers for HF in dilated cardiomyopathy." (PMID 41158506, 2025).
lymph node metastasis (3 papers, 2016 to 2022). "Next, the association of ASPN expression with clinico-pathological parameters, including patients’ age, gender, tumor size, lymph node metastasis, histological grade, depth of invasion, and clinical stage was examined." (PMID 34379688, 2021). "Clinically, asporin can be regarded as a serological biomarker to identify PTC patients with or without lymph node metastasis, and high expression of asporin in PTC tumorous tissues is a risk factor for poor prognosis." (PMID 35600399, 2022).
periodontitis (3 papers, 2020 to 2025). An acute or chronic inflammatory process that affects the tissues that surround and support the teeth. "Our results demonstrate that mice lacking PLAP-1/Asporin show alteration of periodontal ligament structures and acceleration of bone loss in periodontitis." (PMID 37958972, 2023). "Furthermore, the absence of asporin has been linked to periodontal disease, such as periodontitis, which suggest a function in maintenance of periodontal integrity and health." (PMID 32194440, 2020). "Previous studies have reported heterogeneity in gingival fibroblasts in periodontal tissues, with four subsets significantly altered in periodontitis: Fib 1.1 (CXCL1, CXCL2, CXCL13); Fib 1.2 (APCDD1, IGFBP2, MRPS6); Fib 1.3 (APOD, GSN, CFD); and Fib 1.4 (TIMP3, ASPN, COL11A1)." (PMID 40801798, 2025).
prostate tumor (3 papers, 2017 to 2021). "PDGFRβ+ cells shifted from being predominately ASPN− in benign prostate stroma to being comparably ASPN− and ASPN+ in the cribriform prostate tumor microenvironment." (PMID 33600062, 2021). "Furthermore, in asporin null mice, they also found that there are decreased tumor-associated mesenchymal stromal cells, fewer cancer stem cells, reduced tumor vasculature, and increased infiltrating CD8+T cells in the prostate tumor allografts." (PMID 31608236, 2019). "Findings were similar for TNC with a significant increase in the cribriform prostate tumor microenvironment of the lesser abundant ASPN+TNC− cells and ASPN+TNC+ cells in benign prostate stroma and a corresponding significant decrease in the more abundant ASPN−TNC+ cells in benign prostate stroma." (PMID 33600062, 2021).
sarcopenia (3 papers, 2022 to 2025). Progressive decline in muscle mass due to aging which results in decreased functional capacity of muscles. "They ultimately identified five candidate causal proteins associated with sarcopenia, including LILRB2, ASPN, CNTN2, ART4 and SOD2." (PMID 39949133, 2025). "We investigated the putatively potential causal effects of genetically predicted plasma protein levels on sarcopenia-related traits and identified three putatively causal proteins for ALM (LILRB2, ASPN, and CNTN2) and two for handgrip strength (ART4 and SOD2)." (PMID 35938019, 2022).
atherosclerosis (2 papers, 2025 to 2026). A disease characterized by the build-up of fatty material and calcium deposition in the arterial wall resulting in partial or complete occlusion of the arterial lumen. "In studies of atherosclerosis, ASPN has been identified as a key gene linked to the polarization of M2 macrophages." (PMID 40273141, 2025). "Plaque composition was assessed by histological, biochemical, and immunological assays, along with bulk RNA sequencing, to investigate the role of ASPN in atherosclerosis." (PMID 41557654, 2026).
breast ductal adenocarcinoma (2 papers, 2007 to 2015). A breast carcinoma arising from the ducts. "Combined RP and pairwise comparison showed that ASPN was one of the most upregulated genes in lobular carcinomas, when compared with normal ductal (fold change 23.3) and lobular (fold change 22.1) cells as well as with ductal carcinomas (fold change 3.9)." (PMID 17389037, 2007). "Next, we analyzed asporin expression using IHC in breast ductal adenocarcinoma (n = 30) as well as in adjacent non-tumoral tissue and normal breast tissue from breast reduction surgery (n = 10)." (PMID 26327350, 2015).
fibrosis (2 papers, 2021 to 2025). the formation of excess fibrous connective tissue in an organ or tissue in a reparative or reactive process. "Subsequent validation in patient samples further confirmed ASPN’s positive correlation with disease duration and histological fibrosis severity." (PMID 40881699, 2025).
intervertebral disc degeneration (2 papers, 2017 to 2021). "In conclusion, our study provides evidence that asporin is an important risk factor in intervertebral disc degeneration." (PMID 28646230, 2017). "Taken together, these data demonstrated that asporin is upregulated in the nucleus pulposus during intervertebral disc degeneration." (PMID 28646230, 2017). "However, little is known about how asporin is regulated and becomes involved in the pathogenesis of intervertebral disc degeneration." (PMID 28646230, 2017).
lobular carcinoma (2 papers, 2007 to 2025). "The DVL1 gene encoding protein involved in Wnt signaling and the leucine-rich repeat protein ASPN (asporin) were upregulated in lobular carcinomas." (PMID 17389037, 2007). "Asporin was more upregulated in our lobular carcinomas when compared with ductal tumors as well as with normal cell types." (PMID 17389037, 2007). "Overexpression of asporin mRNA in lobular carcinomas was then confirmed by chromogenic in situ hybridization and PCR." (PMID 17389037, 2007). "Likewise, a similar study found that asporin was significantly upregulated in lobular carcinomas than in healthy ducts (fold change of 23.3), whereas it was lightly upregulated, although significantly upregulated again when comparing lobular carcinoma with ductal carcinomas (fold change of 3.9)." (PMID 41463344, 2025).
lung adenocarcinoma (2 papers, 2016 to 2020). A carcinoma that arises from the lung and is characterized by the presence of malignant glandular epithelial cells. "On the other hand, lung adenocarcinoma with high asporin expression had better outcome than patients with low asporin expression." (PMID 27409832, 2016). "Six genes (COL3A1, COL1A2, OGN, COL15A1, ASPN, and MXRA5) and three miRNAs (hsa-miR-29c-3p, hsa-let-7c-5p, and hsa-miR-29b-3p) were related to the survival time of lung adenocarcinoma (LUAD)." (PMID 32300359, 2020).
Obesity (2 papers, 2023 to 2025). Accumulation of substantial excess body fat. "Adipocytes were identified as an unexpected source of asporin in obesity-associated BC, which accumulates in mammary adipose tissue and enhances tumour progression." (PMID 41463344, 2025). "In that study, the expression of three PGs was altered as a result of obesity: serglycin, versican, and asporin." (PMID 37108048, 2023). "The genetic knockout of asporin markedly reduced tumour growth and improved CD8+ T-cell infiltration, thus highlighting that it mediates a stromal–adipose axis promoting tumour immune evasion and progression in obesity-linked BC." (PMID 41463344, 2025).